SPARC (secreted protein acidic and cysteine rich)
Diseases named in the same sentence as SPARC in open-access papers (continued):
Sharing a sentence is not in itself a finding about the gene and the disease.
Obesity (45 papers, 2008 to 2025). Accumulation of substantial excess body fat. "It is worth pointing out that SPARC has been reported to be associated with conditions such liver injury and obesity." (PMID 40299645, 2025). "Collectively, EP3 deficiency reduces the expression and secretion of SPARC within macrophages, thereby accelerating the development of diet-induced obesity in mice." (PMID 40702315, 2025). "Circulating levels of SPARC are increased in obesity and diabetes in both mice and humans, and mice with SPARC deficiency exhibit impaired glucose homeostasis and insulin secretion." (PMID 39872377, 2024). "Increased levels of SPARC are associated with metabolic diseases — including obesity, diabetes, and cardiovascular disease — that are associated with chronic inflammation." (PMID 37781916, 2023). "A previous study has shown that the SPARC gene is associated with human obesity and its expression is increased in adipose tissue of obese individuals." (PMID 35999587, 2022). "Recent studies found that dysregulation of SPARC is associated with a variety of obesity-related diseases, including type 2 diabetes and its complications related to obesity, kidney and liver disease, cardiovascular disease, and cancer." (PMID 35721704, 2022). "SPARC, a profibrotic protein secreted by adipocytes, is implicated in the pathogenesis of inflammation, dyslipidemia, increased cardiovascular risk, obesity, and type 2 diabetes." (PMID 34867780, 2021). "Recently, deletion of SPARC expression has been reported to cause diabetes mellitus in mice, demonstrating that SPARC deficient mice represent a reliable model for obesity and its metabolic complications, including diabetes mellitus." (PMID 33192583, 2020). "In other studies, elevated plasma concentrations of SPARC are associated with diabetes mellitus, inflammation and dyslipidemia and obesity —all risk factors for cardiovascular disease." (PMID 30875406, 2019). "SPARC (secreted protein acidic and rich in cysteine) is a matricellular glycoprotein that plays critical roles in the pathologies associated with obesity and diabetes, as well as tumorigenesis." (PMID 23935929, 2013). "Finally, SPARC is an adipocyte-secreted proinflammatory adipokine, and chronic inflammation in adipose tissue caused by its elevation is an important marker of obesity." (PMID 38977622, 2025). "The significant reduction in SPARC levels after anti-obesity treatments in our study could be due to improved metabolic abnormalities and inflammation associated with obesity." (PMID 37436597, 2023). "Interestingly, obesity is associated with increased circulating SPARC levels in humans and a high level of SPARC is associated with insulin resistance, inflammation, and diabetes." (PMID 37781916, 2023). "The functional enrichment analysis of the DEGs showed clustering around the genes CXCL5, EGF, and SPARC, which are associated with diabetes, obesity, and insulin secretion and enriched in disease ontology terms of metabolic disease, diabetes, and glucose metabolism disease." (PMID 36138412, 2022). "In particular we tested the hypothesis that SPARC is elevated under conditions of necrosis and inflammation, and could be associated with a high risk of fibrosis in obesity-related human liver disease and animal models mimicking NAFLD/NASH." (PMID 29335425, 2018). "In particular, SPARC, as an interesting candidate gene involved in the bone-adipose axis, deserves further investigation with particular focus on human gene polymorphisms affecting obesity rate." (PMID 28831160, 2017). "Furthermore, higher expression of SPARC in adipose tissues is associated with obesity in human individuals and mouse models." (PMID 26110898, 2015). "The influence of SPARC in insulin resistance may also arise from its role in obesity-induced adipose tissue fibrosis and associated metabolic dysfunction by regulating extracellular matrix (ECM) composition and inhibiting adipogenesis." (PMID 24349098, 2013).
Obesity (continued). "However, how adipocyte-derived SPARC controls metabolism and inflammation during obesity and weight loss is unknown." (PMID 37781916, 2023). "The 3 variants (c.1024_1025delTA p.(Ter342fs), c253C > A p.(Leu85Met), and c.230G > T p.(Cys77Phe) in SPARC related to obesity in our study were classified as pathogenic or likely pathogenic according to the ACMG guidelines, suggesting that these variants may be closely related to obesity." (PMID 35999587, 2022). "Both consequences would be due to calcium complex depots enhanced by SPARC that are overexpressed during obesity." (PMID 40299645, 2025). "This family includes molecules, such as SPARC, SPARCL-like 1 (SPARCL1), thrombospondin 1 and 2, and osteopontin, all of which have been implicated in the development of obesity, insulin resistance, and chronic liver diseases." (PMID 40243151, 2025). "SPARC deletion in macrophages abrogated the protection of EP3-overexpression against diet-induced obesity." (PMID 40702315, 2025). "In adipose tissue, SPARC is mainly expressed in stromal cells and adipocytes and is upregulated in patients with obesity and animals." (PMID 40702315, 2025). "Circulating levels and muscle mRNA expression of SPARC are higher in people with obesity and T2D than in lean people." (PMID 40171198, 2025). "Here, we report a novel macrophage-adipocyte interaction counters the development of obesity through EP3-governed macrophage secretion of SPARC, an anti-adipogenic factor, to suppress pre-adipocyte differentiation toward to mature adipocytes." (PMID 40702315, 2025). "SPARC is markedly upregulated in adipose tissues in both obese rodent models and humans with obesity and also has been reported to improve insulin resistance in mice." (PMID 39872377, 2024). "SPARC has recently attracted substantial interest due to its roles in obesity, insulin resistance, and metabolic syndrome, and FGF21 is thought to have therapeutic potential for obesity, T2DM, and NAFLD." (PMID 39391493, 2024). "The overexpression of SPARC at sites, including injury, regeneration, obesity, cancer, and inflammation, reveals its application as a prospective target and therapeutic indicator in the treatment and assessment of disease." (PMID 37577749, 2023). "In mice, adipose tissue remodeling caused by weight loss through CR and low-protein diet feeding decreased, while high-fat diet–induced (HFD-induced) obesity increased SPARC expression in adipose tissue." (PMID 37781916, 2023). "Recently, SPARC has also gained substantial interest due to its roles in obesity, insulin resistance, and metabolic syndrome." (PMID 37436597, 2023). "Therefore, to test whether our findings of reduction of SPARC in adipose tissue in humans undergoing CR are causally linked to enhanced metabolic health, we developed new genetic mouse models to determine the role of SPARC in the context of obesity." (PMID 37781916, 2023). "Collectively, these data demonstrate that reduction in SPARC production from adipocytes protected against obesity by decreasing adiposity with modest increases in EE and enhanced lipolytic response in female mice." (PMID 37781916, 2023). "Collectively, reduction of adipocyte-derived SPARC confers CR-like metabolic and antiinflammatory benefits in obesity by serving as an immunometabolic checkpoint of inflammation." (PMID 37781916, 2023). "Our data also demonstrate that reduction of adipocyte-derived SPARC acted on ATMs in fat to decrease obesity-related inflammation." (PMID 37781916, 2023). "To determine how lowering SPARC protects against diet-induced obesity, we next investigated changes in energy balance upon downregulation of SPARC in adipocytes using indirect calorimetry." (PMID 37781916, 2023). "After 1 year of anti-obesity treatments, SPARC levels decreased significantly throughout the cohort, LEI + topiramate, LEI + liraglutide, and LEI + bariatric/metabolic surgery, where they were groups that showed significant weight loss." (PMID 37436597, 2023).
Obesity (continued). "SPARC is required to maintain glucose homeostasis and insulin secretion in mice with metabolic diseases such as obesity and type 2 diabetes." (PMID 35721704, 2022). "A recent study has revealed that subnetworks of key genes such as SPARC play roles in regulating known genes for obesity, CVD, and T2D." (PMID 35999587, 2022). "For instance, SPARC inhibits adipogenesis and its inactivation leads to an enhancement of high-fat diet-induced obesity." (PMID 33435573, 2021). "This is, for instance, illustrated by the increase of SPARC during both obesity and cancer as well as the SPARC properties to inhibit both adipogenesis and tumor development." (PMID 34827687, 2021). "Diverse pathologies (inflammation, tissues injuries, cancer, etc.)and physiological conditions (obesity, physical activity, etc.)induce the expression/secretion of the matricellular protein, secrete protein acidic and rich in cysteine (SPARC)." (PMID 33435573, 2021). "Increased serum levels of SPARC or its gene overexpression have been reported following numerous physiological and pathological changes including injuries, exercise, regeneration, obesity, cancer, and inflammation." (PMID 34827687, 2021). "While serum SPARC increases with obesity, its levels are reduced following bariatric surgery for weight loss." (PMID 34827687, 2021). "Furthermore, we provide evidence that SPARC exerts a tumour-suppressor effect in OvCa linking inflammation to metabolic programming, a process termed “metaflammation” that has been implicated in diseases associated with inflammation and perturbed bioenergetics as diabetes, obesity and aging." (PMID 30765860, 2019). "Beside the knowledge gap regarding genetic-based alterations of SPARC, the gene is well characterised in the background of obesity." (PMID 28831160, 2017). "In particular, elevated SPARC levels have been proposed to contribute to the pathogenesis of obesity and T2DM by promoting insulin resistance." (PMID 26110898, 2015). "Circulating SPARC is known to increase in obesity on the basis of increased expression and secretion of SPARC in adipose tissue." (PMID 23840838, 2013). "Recent studies suggested that secreted protein acidic and rich in cysteine (SPARC), a novel adipokine, is a key player in the pathology of obesity and type 2 diabetes." (PMID 24349098, 2013). "Recently, secreted protein acidic and rich in cysteine (SPARC), has been suggested as a key player in the pathology of obesity and type 2 diabetes." (PMID 24349098, 2013). "SPARC is reported to be up-regulated in the adipose tissue of different models of murine obesity and its circulating levels correlate with body mass index in humans." (PMID 18302751, 2008). "EP3 agonist treatment mitigates diet-induced obesity in HFD-fed mice via SPARC." (PMID 40702315, 2025). "However, recent studies have revealed pathologic roles for SPARC in adulthood, such as adipose fibrosis, age‐related inflammation, metabolic dysfunction, obesity, and diabetes and diabetic nephropathy and retinopathy." (PMID 41078088, 2025). "SPARC regulates tissue remodeling, impacting obesity-related processes and pain modulation." (PMID 40313396, 2025). "Notably, knockdown of SPARC in Rosa-EP3α/LysMCre mice abrogated the protective effects of macrophage EP3α overexpression against obesity in mice." (PMID 40702315, 2025). "SPARC also causes insulin resistance and is positively correlated with BMI, waist circumference, fasting blood glucose, and fasting insulin; therefore, SPARC may be a key participant in obesity and type-2 diabetes mellitus." (PMID 38977622, 2025). "Thus, EP3 inhibits adipogenesis through promoting release of SPARC from macrophages, suggesting a novel therapeutic target for diet-induced obesity." (PMID 40702315, 2025). "Moreover, these three bacterial strains were significantly associated with certain adipo-myokines related to obesity or inflammation (LIF, FSTL1, FGF21, SPARC, and IL6)." (PMID 39391493, 2024).
Obesity (continued). "Therefore, SPARC would be a key molecular link between physical exercise, obesity, T2D, CVD and inflammation." (PMID 36810547, 2023). "SPARC also improves mitochondrial function, sarcopenia, obesity, T2D, CVD and inflammation." (PMID 36810547, 2023). "Among SPARC’s properties that could lead to possible therapeutic applications, we have anti-inflammatory, anti-ageing, anti-sarcopenia/muscle atrophy and anti-obesity properties, as well as SPARC’s importance for immunity." (PMID 37233608, 2023). "It has been shown that SPARC-null mice were more likely to be affected by Diet-induced obesity." (PMID 34751020, 2022). "Moreover, serum SPARC levels are also known to be elevated in individuals with obesity and T2DM and are positively correlated with BMI and insulin resistance." (PMID 35909571, 2022). "SPARC expression is markedly up-regulated in AT in obese rodent models and humans with obesity, and is positively correlated with metabolic parameters such as fasting insulin and glucose levels, homeostatic model assessment for insulin resistance (HOMA-IR), waist circumference and hsCRP." (PMID 35909571, 2022). "This suggests that SPARC promotes AT inflammation in obesity." (PMID 35909571, 2022). "SPARC and DCN were associated with insulin resistance and obesity." (PMID 35627183, 2022). "Interestingly, the situations in which SPARC is overexpressed are mainly those requiring regeneration, either to repair tissues (injury) or adapt to tissue changes (obesity, exercised muscle, etc.)." (PMID 33435573, 2021). "These properties that SPARC has within the regeneration contexts could have a variety of applications, such as in obesity, cancer, sarcopenia, diabetes and bioengineering." (PMID 33435573, 2021). "Therefore, increased plasma SPARC in patients with obesity would play a role in induction of insulin secretion." (PMID 33067534, 2020). "In addition, in patients with gestational diabetes mellitus and obesity SPARC levels correlated with dyslipidemia and insulin resistance." (PMID 29335425, 2018). "Among these proteins, secreted protein acidic and rich in cysteine (SPARC) attracted our attention in the context of T1DM because we previously reported that SPARC might play a vital role in resistance to obesity development." (PMID 26110898, 2015). "The implication of SPARC in diabetic liver may be correlated with a causal role of SPARC in T2DM and obesity." (PMID 26110898, 2015). "Indeed, SPARC has been observed in atherosclerotic regions, and SPARC plasma levels were found to be elevated in obesity and CAD patients." (PMID 20976234, 2010). "Considering that there is shared fundamental biology between SPARC’s role on adipose tissues during obesity and its role on cancer and bone microenvironments, it is possible that SPARC may affect cancer progression or bone remodeling by acting on resident myeloid cells." (PMID 37781916, 2023). "Given that SPARC is a secreted protein, future studies to neutralize this matrikine through specific monoclonal antibodies may offer potential approaches to target NLRP3-driven inflammation and obesity-associated diseases." (PMID 37781916, 2023). "The expression of SPARC is dramatically upregulated in the adipose tissue of patients with obesity and in obese rodent models, and circulating levels of SPARC are also elevated in patients with obesity and T2DM and show a positive correlation with BMI and insulin resistance." (PMID 38074873, 2023). "Importantly, the fact that SPARC is overexpressed during pathological situations such as obesity and cancer, as well as during physical activity (physiological adaptation), further indicates that it could represent feedback." (PMID 33435573, 2021). "In addition, studies suggested the involvement of SPARC in the pathogenesis of obesity and T2DM." (PMID 33192583, 2020).
Obesity (continued). "Alterations to SPARC levels or activity have been associated with several common human diseases such as osteoporosis, arthritis, cancer, heart disease, obesity, and independent of obesity, type 2 diabetes." (PMID 23840838, 2013). "Like SPARC and MMP-2, other myokines are involved in ECM remodeling, a process that is altered in muscle of people with obesity and T2D but improved by bariatric surgery." (PMID 40171198, 2025). "SPARC is highly expressed in obesity and type 2 diabetes mellitus (T2DM), and levels of SPARC in plasma are relatively high in T2DM patients." (PMID 37577749, 2023). "Here, based on unbiased identification of SPARC as a CR-inhibited gene in human adipose tissue, we sought to determine whether adipocyte production of SPARC is a potential partial CR-mimetic target that can be harnessed to regulate metabolic inflammation during obesity." (PMID 37781916, 2023). "SPARC knockout mice show increased white AT mass and adiposity after HFD consumption, suggesting that SPARC limits AT expansion during obesity." (PMID 35909571, 2022). "Hence, adipose-secreted SPARC could have a role in obesity and diabetes." (PMID 35909571, 2022). "Therefore, SPARC might represent a key player in the pathology of obesity and metabolic syndrome." (PMID 33192583, 2020). "Therefore, it seems that SPARC may contribute to metabolic dysregulation in obesity." (PMID 29335425, 2018). "In summary, the activation of EP3 receptor inhibits HFD-induced obesity in mice by promoting macrophage releasing SPARC via the PKA/Sp1/Dnmt1,3a pathway, indicating that the EP3 receptor may be an attractive therapeutic target for obesity." (PMID 40702315, 2025). "Similarly, weight loss through CR and low-protein diet feeding in mice decreases SPARC expression, while HFD-induced obesity increases SPARC expression in adipose tissue." (PMID 40243151, 2025). "Also, matricellular proteins, including thrombospondins, secreted protein acidic and rich in cysteine (SPARC), and osteopontin, are upregulated in obesity and metabolic syndrome, inducing the deposition of collagen and the proliferation of cardiac fibroblasts." (PMID 39203917, 2024). "Brain-derived neurotrophic factor (BDNF), secreted protein acidic and rich in cysteine (SPARC), fibroblast growth factor 21 (FGF-21), growth differentiation factor 15 (GDF-15) are examples of such cytokines which have therapeutic potential in obesity and metabolic diseases." (PMID 37436597, 2023). "Although the precise roles of SPARC in tumors are not still obvious, dysregulation of this protein has been reported in obesity and diabetes." (PMID 34751020, 2022). "This represents another illustration of how SPARC counteracts the “negative” regeneration environment, since obesity itself represents a status of impaired regeneration." (PMID 33435573, 2021). "Given that obesity-related increase in NLRP3 inflammasome activation is a predominant regulator of IL-1β production and decreased health span, we next tested whether SPARC gain of function impacts the inflammasome." (PMID 37781916, 2023). "In the absence of SPARC, mice show enhanced diet-induced obesity." (PMID 36810547, 2023). "Thus, SPARC reverses numerous negative impacts of obesity, in addition to other factors, such ageing and diverse obesity-related and age-related health conditions, that render individuals more susceptible to COVID-19." (PMID 37233608, 2023). "This supports our hypothesis, which states that to see a SPARC deficiency-related difference in the adipocyte, we need to induce obesity as HFD-induced obesity is enhanced in the absence of SPARC." (PMID 35208200, 2022). "Our data suggest that levels of SPARC are reduced in islets from donors with diabetes and that it has a role in insulin secretion, an effect which appears independent of SPARC’s modulation of obesity-induced insulin resistance in adipose tissue." (PMID 23840838, 2013).